CRP (C-reactive protein)
Diseases named in the same sentence as CRP in open-access papers (continued):
Sharing a sentence is not in itself a finding about the gene and the disease.
depression (continued). "Concentrations of TNF and IL-6 are elevated in depressed individuals compared to healthy ones, while CRP concentrations have been associated with depression scale scores and explained 20% of the obesity-related alteration in depression scores at follow-up." (PMID 33546219, 2021). "For instance, elevated CRP was reported to be protective for schizophrenia but a risk factor for depression, while other studies have reported null findings for depression." (PMID 34280516, 2021). "For men, higher interleukin-6 levels and higher hs-CRP levels were associated with depression and social isolation, higher leptin levels predicted depression and social isolation." (PMID 33614574, 2021). "We used data from the ALSPAC birth cohort to examine temporality and specificity of association of IL-6 and CRP levels at age 9 and risks for psychosis and depression at age 24, addressing some of the key gaps in the literature." (PMID 33684738, 2021). "CRP concentration was associated with depressive and anxiety symptom scores and with probable diagnoses of depression and generalised anxiety disorder (GAD) in a dose-response fashion." (PMID 34505025, 2021). "Elevated levels of CRP have been observed in people with bipolar disorder and have been associated with an increased risk of depression." (PMID 33517931, 2021). "Prenatal PM10 and PM2.5 exposures have been linked to elevated maternal CRP and Il-6 levels and considerable evidence implicates these neuroinflammatory pathways in depression pathophysiology." (PMID 34838014, 2021). "Higher levels of CRP at baseline are associated with an increased risk of depression in subsequent follow-ups and systematic review and meta-analysis." (PMID 33672126, 2021). "Similar to previous studies, we found that fewer women use e-cigarettes, yet are at elevated risk for depression (50%) and serum CRP ≥ 8.0 mg/L (100%) compared to men." (PMID 34639705, 2021). "Chronically elevated CRP is also associated with cardiovascular disease, major depressive disorder, generalized anxiety disorder, and schizophrenia, as well as greater severity of symptoms in patients with schizophrenia." (PMID 33602170, 2021). "For anxiety, associations were mainly limited to CRP and irritability, a symptom also commonly present in depression." (PMID 34135474, 2021). "There were no sex differences in any variables across the 91 males and 130 females, but depression status did confound the association between global CM and CRP." (PMID 34867491, 2021). "We explored and adjusted for relevant variables previously linked to CVD: MMP-2, MMP-9, MMP-14, TIMPS, galectin-3, CRP, metabolic variables, life style variables, depression, and thyroid disease." (PMID 34702365, 2021). "Cross-sectional associations of inflammatory markers with depression status were tested and showed positive associations with IL-6 and CRP." (PMID 33064180, 2021). "Using genetic variants in the IL6R and CRP gene loci, we have found that higher genetically predicted IL-6 activity was associated with increased risk of depression, but higher genetically predicted CRP levels were associated with decreased risk of depression." (PMID 34505025, 2021). "Associations of serum CRP concentrations with depression and anxiety were mostly stronger in women than men." (PMID 34505025, 2021). "At the same time, we show evidence for disorder-specificity suggesting that CRP is more strongly associated with depression compared to anxiety." (PMID 34505025, 2021). "Another study suggests that the effectiveness and severity of Agomelatine in the treatment of depression are associated with circulating CRP levels in depression patients." (PMID 34292876, 2021). "Increased CRP levels have clinical relevance for depression, as CRP ⩾3 mg/L was associated with an increased risk of developing depression later in life (Au, Smith, Gariepy, & Schmitz, 2015), and a lack of response to antidepressant medication." (PMID 33731235, 2021).
depression (continued). "Another large population-based study in > 350 000 individuals concluded that the risk factors of CVD [i.e. inflammatory markers (CRP, IL-6) and biomarker (triglycerides)] are likely causal for the development of depression." (PMID 34078486, 2021). "In light of the significant depression-related differences in functional connectivity, we next estimated the association between CRP and functional connectivity using data from all depressed cases (excluding controls)." (PMID 34535766, 2021). "Multiple studies have also found that some subtypes of depression are associated with increased levels of markers of systemic inflammation, such as interleukin 6 (IL-6) and C-reactive protein." (PMID 34468686, 2021). "Anxiety symptoms are also often present in patients with depression, but studies testing the association between CRP levels and anxiety symptoms in patients with depression are scarce." (PMID 34729541, 2021). "•Elevated CRP (≥3mg/L) was associated with higher depression severity, fatigue, state anxiety, and stress." (PMID 34729541, 2021). "Based on data from the UK Biobank cohort, a large general population cohort, we report that circulating CRP concentrations are associated with depressive and anxiety symptoms and with probable diagnoses of depression and GAD in a linear, dose-response fashion." (PMID 34505025, 2021). "Taken together, these results suggest that CRP is associated with anxiety, but these associations are strongly related to the presence of underlying depression." (PMID 34729541, 2021). "Adjusted logistic regression models showed cross-sectional associations of C-reactive protein and IL-6 with depression." (PMID 33064180, 2021). "This is because a protective effect of CRP on schizophrenia risk fully attenuated in MVMR analysis after accounting for the effects of IL-6 and sIL-2Rα, and we didn’t find evidence for an association of CRP with depression, in line with other MR evidence." (PMID 34280516, 2021). "The most commonly measured inflammatory marker has been CRP, which, in keeping with our findings, has been found to be associated with depression in people with both type 2 diabetes and depression." (PMID 33064180, 2021). "The increased risk for overweight patients with depression to have clinically elevated hsCRP ⩾3 mg/L is concerning, as CRP is a predictor of all-cause mortality." (PMID 33731235, 2021). "Several studies have supported associations of higher CRP or IL-6 levels with increased depression severity." (PMID 34729541, 2021). "Elevated peripheral markers of inflammation—as measured by C-reactive protein (CRP)—have been associated with depression and with lower cortico-striatal functional connectivity." (PMID 32929215, 2021). "Serum CRP is a marker of current active peripheral inflammation and this was associated with current depression symptoms, particularly somatic symptoms." (PMID 33221487, 2021). "It is also important to investigate if immunological markers beyond CRP and IL-6 are potentially causally associated with depression, and to identify potential cellular drivers for IL-6 dysfunction." (PMID 34135474, 2021). "An increased CRP level has been documented to be a useful biomarker for predicting a nine-year major depressive disorder diagnostic status change." (PMID 34943627, 2021). "High consumption of processed and red meats was associated with higher levels of low-grade inflammation (C-reactive protein) and subsequent brain atrophy, which is in turn positively associated with depression." (PMID 34024764, 2021). "In the adjusted model for reaction time, only serum CRP level quintile five and recurrent major depression (severe) remained significantly associated with lower cognitive performance." (PMID 33517931, 2021). "In patients with depression, plasma CRP concentration was reported to be associated with left basal ganglia glutamate levels, which, in turn, was associated with psychomotor slowing and anhedonia." (PMID 34729541, 2021).
depression (continued). "Evidence was compatible with linear associations of CRP with both depression and anxiety across all analyses using symptom scores and probable diagnoses as outcomes (P-value for all quadratic terms >0·05)." (PMID 34505025, 2021). "Increased CRP levels raised the risk of subsequent depression by 1.58 (95% CI 1.010 to 2.16) and ln WBC by 1.88 (95% CI 1.04 to 3.42), even when adjusting for sociodemographic, physical health, health behavior variables, and baseline depression symptoms." (PMID 33500534, 2021). "Our study showed that some inflammatory markers, especially CRP and IL-6, appeared to be associated with depression status." (PMID 33064180, 2021). "Elevated (hs)CRP levels have also been associated with mental health issues, e.g., to increased risk for depression or psychological distress." (PMID 34360212, 2021). "This is because we found that genetically predicted increases in IL-6 were associated with an increased risk of schizophrenia and depression, while the association with genetically-predicted increased CRP fully attenuated in schizophrenia." (PMID 34280516, 2021). "Interleukin (IL)-1β, IL-6, IL-10, monocyte chemoattractant protein-1, tumor necrosis factor-alpha, C-reactive protein, and phospholipase A2 contribute to depression, which is also associated with type 2 diabetes." (PMID 34639601, 2021). "For example, long term elevation of inflammatory markers such as C-reactive protein (CRP) is associated with an increased risk of cardiovascular complications and mental health issues such as depression." (PMID 35010326, 2021). "The unadjusted model for reaction time z-score showed serum CRP level quintiles four and five, BD-I, recurrent major depression (severe), and recurrent major depression (moderate) were significantly associated with lower cognitive performance." (PMID 33517931, 2021). "Second, we report some evidence in support of a causal relationship between IL-6 and major depression after controlling for CRP and sIL-2Rα." (PMID 34280516, 2021). "Clinical studies have reported fairly consistently that circulating inflammatory markers, such as CRP and several cytokines, are related to increased risk for depression." (PMID 33672126, 2021). "None of the traditional risk factors for CVD such as low grade inflammation (increased CRP), increased HbA1c, dyslipidaemia, increased blood pressure, physical inactivity, smoking, or the less established risk factor—depression, was associated with MMP-14." (PMID 34702365, 2021). "For men higher C-reactive protein (CRP) levels were associated with social isolation and the presence of depression." (PMID 33614574, 2021). "Depression was associated with a higher CRP level in a cross-sectional study of 14,276 patients in the United States." (PMID 34943627, 2021). "Numerous clinical studies have also shown that the increased circulation levels of inflammatory markers such as IL-6 and/or CRP are associated with depression only in males or more strongly in males than females." (PMID 33672958, 2021). "The present study also shows that noted associations between elevated CRP levels and increased risk for psychological distress and depression among the general population hold under conditions of pregnancy." (PMID 33301421, 2021). "Cross-sectional population studies with 5000 to 7000 participants have reported an association between CRP levels and depression." (PMID 34680097, 2021). "Similar divergent MR results have also been reported for schizophrenia and depression, suggesting a protective effect of CRP and a risk-increasing effect of soluble IL-6 receptor (IL-6R) on schizophrenia and depression risk, respectively." (PMID 34135474, 2021). "We have also previously reported that IL-6R variants associated with higher serum IL-6 levels (but decreased IL-6R activity) and CRP variants associated with higher CRP levels are both associated with increased risk of depression in the UK Biobank." (PMID 34135474, 2021).
depression (continued). "Although elevated CRP levels are associated with depression, remarkably lower CRP values were found in the studied CD compared to CN, though both groups had an elevated systemic inflammatory response (CRP levels > 3 mg/L)." (PMID 34743729, 2021). "We have used data from up to 144,890 individuals from the UK Biobank study, a large general population-based cohort, to test associations of circulating CRP concentrations with depression and anxiety." (PMID 34505025, 2021). "On a genetic level, a recent correlation study based on a large genome-wide association study reported an overlap between CRP levels and depression symptoms as well as an association of upregulated IL-6 with suicidality." (PMID 34279714, 2021). "Elevated levels of CRP are associated with increased risk for psychological distress and depression in the general population." (PMID 34680097, 2021). "We examined potential causality using 1-sample and 2-sample Mendelian randomisation (MR) analyses testing associations of genetically-predicted CRP concentration and IL-6 activity with depression and anxiety." (PMID 34505025, 2021). "Genetically-predicted concentration/activity of IL-6 and CRP were associated with both depression and anxiety." (PMID 34505025, 2021). "Circulating markers of inflammation such as interleukin-6 (IL-6) and C-reactive protein (CRP) are associated with depression and CVD in adults." (PMID 34146903, 2021). "Even more so, increased CRP alongside increased homocysteine was associated with the risk of developing post-stroke depression after one year from the stroke." (PMID 34445740, 2021). "Increased inflammation as a risk factor for depression in adolescents was also reported in the recent meta-analysis where increased CRP and IL-6 were associated with subsequent MDD development in children and adolescents." (PMID 34816138, 2021). "Major depressive disorder (MDD) is associated with increased CRP compared with healthy volunteers, and the case-control difference appears higher in treatment-resistant depression." (PMID 34680097, 2021). "In the current study, higher levels of serum hs-CRP were associated with the severity of both depression and anxiety." (PMID 32503468, 2020). "In parallel, the associations between hopelessness and IL-6 and CRP, and between depression and CRP and MMP-9 all disappeared after adjusting for health risk behaviors." (PMID 32075162, 2020). "Subjects who showed a pattern of increasing CRP levels from childhood to early adulthood had a higher risk of moderate/severe depression at 18 years, compared with those who had persistently low CRP." (PMID 31707310, 2020). "Population-based longitudinal studies including our own work have reported that higher concentrations of CRP or IL-6 in childhood or adult life are associated with increased risk of depression or persistent depressive symptoms subsequently at follow-up." (PMID 30886334, 2020). "Based on repeat measure of CRP we report that individuals with increasing levels of inflammation over time, especially during adolescence, have higher risk of moderate/severe depression in early-adulthood." (PMID 31707310, 2020). "A recent genome-wide association study found that common genetic variants for body mass index (BMI) and C-reactive protein (CRP) show overlap with gene variants associated with depression." (PMID 30854996, 2020). "We provide evidence that inflammation, particularly the CRP and IL-6/IL-6R pathways, is causally involved in pathogenesis of depression." (PMID 30886334, 2020). "Another peripheral inflammatory biomarker linked to depression, indicated by several studies, is the C reactive protein (CRP)." (PMID 32961910, 2020). "The increasing group showed a nearly 6-fold increase in average CRP levels between the ages of 15 and 18 years, and showed a significant association with moderate/severe depression at 18 years." (PMID 31707310, 2020).
depression (continued). "The minor allele of CRP +1444C/T polymorphism was associated with decreased risk of depression in women aged at least 65 years." (PMID 33415152, 2020). "It is therefore possible that the strongest link between inflammation and depression lies in a recent increase, and that this is more important than a chronically high CRP level with regards to future risk of depression." (PMID 31707310, 2020). "Increased inflammation can be a shared potential pathophysiological mechanism, as higher levels of inflammation (like C-reactive protein, CRP) are known associates of depression and anxiety." (PMID 34589860, 2020). "In these studies, depression is associated at it's peak with high levels of general inflammation markers such as C-reactive protein (CRP) as well as high levels of pro-inflammatory cytokines such as tumor necrosis factor alpha (TNFα) and interleukin 6 (IL6)." (PMID 33240126, 2020). "Data from population-based studies suggest that elevated levels of circulating IL-6 and CRP are associated with particular symptoms of depression, such as fatigue, sleep and appetite disturbance, which are akin to sickness behaviour." (PMID 33224281, 2020). "Participants in this group had a higher risk of moderate/severe depression at age 18 years, compared with those with persistently low CRP; adjusted odds ratio (OR) = 3.78 (95% Confidence Interval (CI), 1.46–9.81; p = 0.006)." (PMID 31707310, 2020). "Findings from our Mendelian randomization analyses add to the existing literature by showing that reverse causality or residual confounding are unlikely explanations for previously reported associations between IL-6, CRP and depression." (PMID 30886334, 2020). "While the current results do not allow us to draw firm conclusions regarding these associations between markers of inflammation and depression, our data suggests other inflammatory biomarkers are likely more interesting to further explore than CRP." (PMID 32993799, 2020). "For example, in the context of lung cancer, elevated CRP levels are associated with depression in patients with metastatic lung cancer (Mcfarland, Shaffer, Breitbart, Rosenfeld, & Miller, 2018)." (PMID 32790154, 2020). "Other studies have also found a longitudinal association between circulating IL-6 and CRP levels and risk of depression at follow-up." (PMID 31707310, 2020). "Higher BMI at both ages 9 (OR = 1.27; 95 % C.I. 1.10−1.48) and 13 (OR = 1.23; 95 % C.I. 1.09−1.38) years was associated with depression with raised CRP at age 18 years." (PMID 32339985, 2020). "A recent study using Mendelian randomization to elucidate shared mechanisms underlying the association of depression and coronary heart disease provided evidence that triglycerides, IL-6 and CRP are causally related to depression." (PMID 32228541, 2020). "In this study, serum CRP level above 0.85 mg/dL was associated with the increased risk of depression after adjusting for potential confounders." (PMID 31996746, 2020). "Mendelian randomization analyses suggested that triglycerides, interleukin-6 (IL-6), and C-reactive protein (CRP) are likely causal risk factors for depression." (PMID 30886334, 2020). "We also found an interaction between CRP and both BMI and triglycerides on risk of depression, suggesting that inflammation and cardiometabolic factors work together to increase the risk of depression." (PMID 32339985, 2020). "A few studies have examined the relationship between circulating CRP and risk of post-stroke depression." (PMID 31996746, 2020). "Similar to depression, anxiety disorder was associated with elevated levels of CRP and ESR, even after elimination of confounding factors." (PMID 33235810, 2020). "Higher CRP concentrations have been linked to an increased risk of hospitalization due to depression." (PMID 33255237, 2020). "Even some polymorphisms of pro-inflammatory cytokine genes, including IL-1β, TNF, and CRP, appeared to be linked with depression and treatment response." (PMID 32517269, 2020).